TICRR (TOPBP1 interacting checkpoint and replication regulator)
Description:
Regulator of DNA replication and S/M and G2/M checkpoints. Regulates the triggering of DNA replication initiation via its interaction with TOPBP1 by participating in CDK2-mediated loading of CDC45L onto replication origins. Required for the transition from pre-replication complex (pre-RC) to pre-initiation complex (pre-IC). Required to prevent mitotic entry after treatment with ionizing radiation.
Synonyms: C15orf42; MGC45866; FLJ41618; Treslin; SLD3
Tractability: PROTAC: ubiquitination databases record sites on it.
Gene: Protein-coding gene on chromosome 15 (89,575,469 to 89,631,056, forward strand). Ensembl gene ENSG00000140534.
Subcellular location: Nucleus
Subcellular location (Human Protein Atlas): Nucleoplasm
Pathways (Reactome):
Cell Cycle: Cyclin A/B1/B2 associated events during G2/M transition
Gene Ontology:
Molecular function: chromatin binding; protein binding
Biological process: regulation of DNA-templated DNA replication initiation; DNA repair; DNA replication; mitotic DNA replication checkpoint signaling; mitotic G2 DNA damage checkpoint signaling; response to ionizing radiation
Cellular component: nucleoplasm; nucleus
Genetic constraint (gnomAD): Loss-of-function variants: 128 observed, 171.14 expected, observed/expected ratio (o/e) 0.75, 90% interval 0.65 to 0.87. The upper end of that interval is the gene's LOEUF score, 0.87, which puts it in group 3 of 6, group 1 being the genes least tolerant of losing a copy. Missense variants: 2,471 observed, 2,304.6 expected, observed/expected ratio (o/e) 1.07, 90% interval 1.04 to 1.11. Synonymous variants: 959 observed, 885.48 expected, observed/expected ratio (o/e) 1.08, 90% interval 1.03 to 1.14.
Homologues: Orthologues: chimpanzee TICRR (99% identical), macaque TICRR (96% identical), dog TICRR (73% identical), pig TICRR (73% identical), mouse Ticrr (68% identical), rat Ticrr (68% identical), tropical clawed frog ticrr (37% identical), Caenorhabditis elegans tres-1 (10% identical).
Diseases named in the same sentence as TICRR in open-access papers:
TICRR is named in the same sentence as 18 diseases in open-access papers, as found by Europe PMC text mining. Sharing a sentence is not in itself a finding about the gene and the disease. The quoted sentences say what the papers report.
breast carcinoma (3 papers, 2019 to 2022). "In a different study focusing on breast cancer, TICRR showed a similar effect on tumorigenesis, as silencing of TICRR significantly inhibited DNA replication, arrested cell cycle progression, and activated DNA damage." (PMID 33505430, 2020). "The depletion of TICRR can significantly block breast cancer cell proliferation, migration and tumor growth in vitro or in vivo, suggesting it to be a promising therapeutic target for breast cancer treatment." (PMID 31275851, 2019).
papillary renal cell carcinoma (3 papers, 2020 to 2025). A rare subtype of renal cell carcinoma, arising from the renal tubular epithelium and showing a papillary growth pattern, which typically manifests with hematuria, flank pain, palpable abdominal mass or nonspecific symptoms, such as fatigue, weight loss or fever. "Consistent with this, broader literature links TICRR overexpression to adverse outcomes in other cancers (e.g., endometrial and papillary renal cell carcinoma) and to cell-cycle/replication control, underscoring the generalizability of our findings." (PMID 41445727, 2025).
endometrial cancer (2 papers, 2021 to 2024). Primary or metastatic malignant neoplasm involving the endometrium (mucous membrane that lines the endometrial cavity). "Silencing of TICRR and PPIF led to enhance the expression of epithelial marker E-cadherin and decrease the mesenchymal marker N-cadherin and metastasis associated genes MMP9 as well as proliferation-related marker CCND1, suggesting their involvement in the progression of endometrial cancer." (PMID 33495413, 2021). "Additional co-expression analysis studies have shown that AKT1, TICRR, PPIF, ANO1, and PTGDS are possible regulators of endometrial cancer tumorigenesis." (PMID 39596419, 2024). "We then evaluated the expression patterns of TICRR and PPIF in a panel of endometrial cancer cell lines." (PMID 33495413, 2021). "Meanwhile, we found that TICRR and PPIF positive staining were present at a higher level in tissues with endometrial cancer than in tissues of paracancer endometrium." (PMID 33495413, 2021). "TICRR and PPIF may promise to be potential therapeutic targets for endometrial cancer." (PMID 33495413, 2021). "Through a series of in vitro experiments, we found that silencing TICRR or PPIF resulted in a significant suppression of cell proliferation and migration and elevated the effect of progesterone, suggesting their critical role in the progression of endometrial carcinoma." (PMID 33495413, 2021).
lung adenocarcinoma (2 papers, 2023 to 2025). A carcinoma that arises from the lung and is characterized by the presence of malignant glandular epithelial cells. "In the present study, we identified a significant association between TICRR expression and poor prognosis in patients with lung adenocarcinoma." (PMID 41445727, 2025). "In this study, we comprehensively investigated the oncogenic role of TICRR in lung adenocarcinoma (LUAD)." (PMID 41445727, 2025). "Functional suppression of TICRR significantly attenuated the proliferative and metastatic capacities of lung adenocarcinoma cells, highlighting TICRR as a promising therapeutic target in lung adenocarcinoma." (PMID 41445727, 2025). "TICRR has been identified as a robust prognostic biomarker in lung adenocarcinoma (LUAD) due to its involvement in critical biological processes such as immune activation, cell cycle regulation, RNA modification, and tumor energy metabolism." (PMID 38152367, 2023). "Taken together, TICRR has emerged as a promising prognostic biomarker in lung adenocarcinoma (LUAD), with implications in immune activation, cell cycle regulation, RNA modification, and tumor energy metabolism." (PMID 38152367, 2023).
breast invasive carcinoma (1 paper, 2020). "Overexpression of TICRR has been observed in several cancers, such as breast invasive carcinoma and liver hepatocellular carcinoma." (PMID 33505430, 2020). "Moreover, TICRR was also upregulated in tumors of other organs, such as breast invasive carcinoma, colon adenocarcinoma, and glioblastoma multiforme." (PMID 33505430, 2020).
Kidney Chromophobe (1 paper, 2024). "However, the expression of TICRR was remarkably lower in KICH (Kidney Chromophobe), KIRC (Kidney renal clear cell carcinoma), and KIRP (Kidney renal papillary cell carcinoma)." (PMID 37266876, 2024).
lung carcinoma (1 paper, 2025). "Collectively, these findings demonstrate that TICRR knockdown significantly suppresses the proliferation, invasion, and migration of lung cancer cells, highlighting its potential role as an oncogenic factor." (PMID 41445727, 2025). "We further assessed TICRR expression in a panel of lung cancer cell lines (H2228, H3122, H1975, H1299, HCC827, PC-9, and A549) and compared them with the normal lung epithelial cell line BEAS-2B." (PMID 41445727, 2025). "Consistently, immunohistochemical staining of tissue sections demonstrated higher TICRR protein expression in lung cancer." (PMID 41445727, 2025). "Besides, preliminary functional data support a model wherein TICRR promotes lung cancer pathogenesis by modulating the PI3K/AKT/mTOR pathway and its downstream network." (PMID 41445727, 2025). "In vitro, TICRR knockdown suppressed Lung cancer progression." (PMID 41445727, 2025).
lung squamous cell carcinoma (1 paper, 2023). "TICRR was significantly upregulated in most cancer types, including LUAD, lung squamous cell carcinoma (LUSC), and others." (PMID 38152367, 2023).
cancer (10 papers, 2019 to 2025). A tumor composed of atypical neoplastic, often pleomorphic cells that invade other tissues. "Collectively, the TICRR gene is closely associated with adverse patient prognosis and malignant tumor phenotypes." (PMID 41445727, 2025). "Cox regression analysis indicated the overexpression of TICRR was associated with poor survival in several cancers." (PMID 38152367, 2023). "TICRR-associated DEGs were also enriched in cancer pathways, especially the cell cycle-related Hedgehog signaling pathway." (PMID 33505430, 2020). "RT-qPCR showed markedly higher TICRR mRNA expression in cancer cells, with the highest level observed in H1299 cells." (PMID 41445727, 2025). "TICRR is an essential checkpoint and replication regulator and is upregulated in all types of cancer with poor prognosis." (PMID 40048261, 2025). "In our research, we found that TICRR was dramatically highly expressed in a variety of cancer types including HCC, compared with normal tissues based on TCGA database." (PMID 37266876, 2024). "The results showed that TICRR was radically highly expressed in different types of cancers compared with normal tissues." (PMID 37266876, 2024). "Silencing the TICRR gene affects cysteine metabolism and modifies cancer-related pathways, with decreased cell cycle and increased B/T cell receptor signaling." (PMID 38152367, 2023). "In this study, The Cancer Genome Atlas (TCGA)-LUAD dataset and Gene Expression Omnibus (GEO) were acquired to investigate the differential expression of TICRR in various cancers between tumor and normal tissues." (PMID 38152367, 2023). "When compared to normal samples, a notable increase in TICRR expression was observed in 17 different cancer types, The expression level of TICRR is significantly upregulated in LUAD (p<0.0001)." (PMID 38152367, 2023). "TICRR expression is significantly upregulated in most cancer types and is closely related to survival prognosis." (PMID 38152367, 2023). "TopBP1-interacting checkpoint and replication regulator (TICRR) is a DNA replication initiation regulator upregulated in various cancers." (PMID 33505430, 2020). "In conclusion, we reveal that TICRR is an important oncogenic factor that promotes proliferation of cancer cells by enhancing both initiation and progression of DNA replication." (PMID 31275851, 2019). "The critical role of TICRR in regulating DNA replication in cancers suggests that this gene has high potential for clinical applications." (PMID 31275851, 2019). "The obtained evidence collectively lends support to a critical role of TICRR in tumorigenesis through regulating DNA replication in cancer cells, it is then possible that this gene would have great potential in clinical prognosis." (PMID 31275851, 2019). "Therefore, overexpressed TICRR seemed to dampen tumor immunity, help cancer cells escape from elimination, and finally accelerate tumorigenesis." (PMID 33505430, 2020). "Based on TCGA database, we determined the expression of TICRR mRNA in different cancers." (PMID 33505430, 2020). "In addition, higher expression of TICRR predicts poor clinical outcome, making it a promising marker for cancer prognosis." (PMID 31275851, 2019). "In conclusion, our study shows that TICRR is involved in tumorigenesis by regulating DNA replication, acting as a common biomarker for cancer prognosis and could be a promising target for drug-development and cancer treatment." (PMID 31275851, 2019). "Furthermore, we found that TICRR depletion significantly inhibited cancer cell migration in vitro as revealed by the wound healing and transwell assays." (PMID 31275851, 2019).
cancer (continued). "Given its key role in DNA replication, we hypothesize that over-expression of TICRR may contribute to rapid cellular proliferation of cancer cells via accelerating the hyper-replication of DNA." (PMID 31275851, 2019). "Indeed, among the numerous differentially expressed genes (DEGs) recently identified via analyzing 5,540 cancerous transcriptomes, we found that TICRR is consistently up-regulated expression across all the cancer types under analysis." (PMID 31275851, 2019). "Thus, the high initiation of cancer cell resulted from high expression level of TICRR may account for the observations that cancer cells have higher origin activity." (PMID 31275851, 2019). "SCIN, LRP1B, CPNE3, TICRR, and PPP1R7 are connected to cancer cell invasion, migration, proliferation, and apoptosis." (PMID 37628788, 2023). "Meanwhile, we knocked down the expression of TICRR and PPIF in the cancer cell lines by transfection of siTICRR and siPPIF respectively, siTICRR-1 and siPPIF-2 with high transfection efficiency were used for subsequent experiments." (PMID 33495413, 2021). "Genes TICRR and PPIF were significantly overexpressed in cancer cells than in normal endometrial epithelial cells (EEC) compared with other genes, suggesting they may play a pivotal role in oncogenesis and were selected for the following research." (PMID 33495413, 2021).
tumor (9 papers, 2019 to 2025). "Despite these studies confirming the association of TICRR with tumor development, its mechanism of action in tumors, particularly in LUAD, remains unclear." (PMID 41445727, 2025). "Additionally, tumor mutation burden (TMB) analysis revealed that high TICRR expression was associated with increased TMB." (PMID 41445727, 2025). "To elucidate the potential role of TICRR in tumor immunity, we assessed its relationship with key immune checkpoint molecules." (PMID 41445727, 2025). "Mechanistically, TICRR was found to facilitate tumor initiation and progression through activation of the PI3K/AKT signaling cascade." (PMID 41445727, 2025). "In summary, our integrated multi-omics analysis and functional validation establish TICRR as an oncogenic driver in LUAD that promotes tumor proliferation, invasion, and metastatic dissemination." (PMID 41445727, 2025). "Analysis of the TCGA-LUAD cohort demonstrated a significant upregulation of TICRR in tumor tissues, corroborating our previous findings." (PMID 41445727, 2025). "RT-qPCR analysis revealed that TICRR mRNA levels were significantly elevated in tumor tissues compared to matched controls." (PMID 41445727, 2025). "Currently, some studies have already demonstrated that TICRR is overexpressed and involved in tumor carcinogenesis, progression, and chemotherapeutic drug resistance process." (PMID 37266876, 2024). "Our research has illuminated that TICRR is highly expressed in tumor tissues compared to normal tissues." (PMID 38152367, 2023). "In LUAD, TICRR expression was positively correlated with tumor stage and was increased in smoking, male, and high tumor mutational burden (TMB) patients." (PMID 38152367, 2023). "Concurring with RNA-Seq analysis in TCGA, further functional experiments in vitro confirmed that the candidate gene TICRR was upregulated in tumor samples and regulated HCC progression." (PMID 35419294, 2022). "Depletion of TICRR significantly inhibited tumor cell growth, colony formation and migration in vitro, and strikingly inhibited tumor growth in the xenograft model." (PMID 31275851, 2019). "Importantly, functional assays demonstrated that TICRR promotes tumor proliferation, invasion, and migration." (PMID 41445727, 2025). "TOPBP1 interacting checkpoint and replication regulator (TICRR), a hub gene of the Cdk2-mediated initiation step of DNA replication, has been shown an essential role in tumorigenesis by accelerating the DNA replication of tumor cells." (PMID 38152367, 2023). "Enrichment analysis revealed that TICRR could influence tumor proliferation and prognosis via activating pathways involving cell cycle, DNA repair, DNA replication, cysteine metabolism, oxidative phosphorylation, and ubiquitin-mediated proteolysis pathways." (PMID 38152367, 2023). "We speculate that overexpression of TICRR may reduce the anti-tumor effect by inhibiting the mature differentiation and expression of immune infiltration T cells and macrophage cells." (PMID 38152367, 2023). "Given the key role of TICRR in DNA replication initiation as well as the observation that alteration of TICRR level changed DNA initiation, we proposed that the reduced viability and tumor growth induced by TICRR knockdown are attributable to the deficiency of DNA replication." (PMID 31275851, 2019). "Indeed, we reveal that TICRR depletion strikingly inhibited tumor cell proliferation, migration in vitro and tumor growth in vivo." (PMID 31275851, 2019).
tumor (continued). "Mechanistically, TICRR’s biological role is consistent with regulation of DNA replication initiation and S-phase progression; depletion of TICRR impairs both origin firing and fork progression, induces DNA damage responses and cell-cycle arrest, and thereby suppresses tumor growth." (PMID 41445727, 2025). "Interestingly, TICRR also showed a positive correlation with tumor proliferation characteristics." (PMID 41445727, 2025). "Thus, the expression of TICRR may be regulated by the m5C-driven methylation and then affects the tumor progression of LUAD." (PMID 38152367, 2023). "Additionally, TICRR was demonstrated as a tumor-driver gene for this deadly disease." (PMID 35419294, 2022). "We also noticed that TICRR at mRNA level was negatively correlated with OS in HCC patients, suggesting its potentially important role in tumor progression." (PMID 35419294, 2022). "This study further demonstrates DDR pathway may affect the cell cycle by enhancing the TICRR expression, promoting LUAD tumor proliferation." (PMID 38152367, 2023). "As a critical gene involved in the cell cycle, TICRR could activate the DDR pathway and allow the tumor cells to proliferate and avoid repairing DNA damage." (PMID 38152367, 2023). "We have confirmed that TICRR is overexpressed in LUAD, and we speculate that its impact on normal cell cycle processes may contribute to carcinogenesis and tumor progression." (PMID 38152367, 2023).
TICRR also shares sentences with these, for which no sentence is quoted: brain tumors (1 paper); cervical cancer (1); colon adenocarcinoma (1); glioblastoma multiforme (1); Gorlin syndrome (1); hypertrophic cardiomyopathy (1); Macrocephaly (1); nasopharyngeal carcinoma (1).